IL6 (interleukin 6)
Diseases named in the same sentence as IL6 in open-access papers (continued):
Sharing a sentence is not in itself a finding about the gene and the disease.
psychosis (121 papers, 2009 to 2026). "Our findings suggest that TNF-α and IL-6 are selectively associated with impairments in social cognition – specifically emotion recognition and undermentalization – in early psychosis, highlighting their potential as biomarkers and therapeutic targets." (PMID 40637145, 2025). "In this context, examining the interleukins (IL-1β, IL-2, IL-6, IL-10) in these patients offers a promising path toward understanding the early immunological disturbances associated with psychosis." (PMID 41008291, 2025). "Nevertheless, elevated levels of IL-6 are present years prior to the onset of psychosis and have been associated with childhood adversities." (PMID 37592817, 2024). "Subgroup analyses confirmed the reliability of these connections, highlighting that IL-6 plays a crucial role in the biological processes associated with the development of first-episode psychosis." (PMID 39273641, 2024). "Evidence suggests a potentially causal role of interleukin 6 (IL-6), a pleiotropic cytokine that generally promotes inflammation, in the pathogenesis of psychosis." (PMID 36963796, 2023). "Elevated IL-6 cerebrospinal fluid levels have a strong association with psychosis and acute confusional state in patients with SLE." (PMID 37841263, 2023). "We focused on IL-6 in the current investigation given consistent evidence on the association between IL-6 and psychosis." (PMID 36572669, 2022). "According to a longitudinal follow-up study, subjects with high serum IL-6 levels at the age of 9 years had a twofold increased risk of psychosis at the age of 18 years old compared with HCs." (PMID 36590607, 2022). "Another previous research showed that compared with those who did not transition, at-risk mental state (ARMS) subjects who experienced psychosis had higher median IL-6 levels." (PMID 36590607, 2022). "A systematic review and meta-analysis of 16 included studies that reported elevated IL-6 levels in subjects at clinical risk for psychosis." (PMID 35682084, 2022). "Increasing levels of IL-6 (continuous variable) were associated with higher risk of psychotic disorder (adjusted OR = 1.56; 95% C.I., 1.09–2.21; p = 0.014), consistent with a linear dose-response effect (p-value for quadratic term = 0.638)." (PMID 33684738, 2021). "Using IL-6 as a categorical variable, participants in the top, compared with bottom, third of IL-6 at baseline had higher risk of psychotic disorder at follow-up (adjusted OR = 2.60; 95% C.I., 1.04–6.53; p = 0.031)." (PMID 33684738, 2021). "The main inflammatory markers associated with clinical outcome in psychosis were interleukin (IL)-6, IL-10, and C-reactive protein (CRP)." (PMID 33679475, 2021). "The Avon Longitudinal Study of Parents and Children has recently reported twofold increased risk of psychotic disorder at age 18 years for subjects who had higher IL-6 serum levels at age 9 years, in a dose–response manner." (PMID 29163240, 2017). "IL-6 levels are associated with younger psychosis onset, longer duration of illness and worse illness presentation, all indicators of worse disease course." (PMID 27206977, 2016). "Alternatively, as both CT and psychosis are independently associated with elevations in IL-6 and CRP, it can be hypothesized that their overexpression may favour a negative feedback effect with consequent reduction of their production." (PMID 41049865, 2025). "Considering interleukins, increased levels of IL-6 have been evidenced in the nigrostriatal region and cerebrospinal fluid of PD patients, while in patients with meth-associated psychosis, IL-6 and IL-8 are significantly increased in correlation with the severity of the cognitive dysfunctions." (PMID 37691228, 2024). "Shorter sleep duration across childhood, particularly if sustained at all time points, may be considered as a risk for the development of psychosis in adulthood; inflammation as measured by IL-6 level could be one of the potential mechanistic pathways." (PMID 38717746, 2024).
psychosis (continued). "Furthermore, psychotic symptoms in early adulthood were linked to elevated IL-6 levels measured in childhood, years before psychosis onset." (PMID 39273641, 2024). "Moreover, peripheral anti-LPS IgA antibodies levels were also found to be associated with IL-6 elevation and recent suicide attempts in psychosis." (PMID 36311523, 2022). "Similarly, following imputation, participants in the top, compared with bottom, third of IL-6 at age 9 had higher risk of psychotic disorder (adjusted OR = 1.54; 95% C.I., 1.02–2.11) and higher negative symptoms (adjusted β = 0.14; 95% C.I., 0.00–0.29)." (PMID 33684738, 2021). "Supporting this hypothesis, we have previously shown high levels of IL-6 to be associated with smaller hippocampal volume in patients with first episode psychosis." (PMID 33667853, 2021). "Recently, a prospective study from the Avon Longitudinal Study of Parents and Children (ALSPAC), a general population birth cohort, has reported two-fold increased risk of PEs and psychotic disorder at age 18 years for higher serum levels of IL-6 at age 9 years." (PMID 27622678, 2017). "TNF-α and IL-6 showed specific associations with emotion recognition and undermentalization, respectively, suggesting that proinflammatory cytokines may selectively disrupt prefrontal–limbic circuits underlying social cognition in early psychosis." (PMID 40637145, 2025). "Multiple linear regression models were conducted to examine the relationship among IL-6, TNF-α levels and cognitive performance while adjusting for IQ, sex, age, psychosis risk group (HC, CHR, and FEP), and positive symptom severity." (PMID 40637145, 2025). "We investigated associations among IL-6, TNF-α, and neurocognitive performance in 107 participants: individuals at clinical high risk for psychosis (CHR-P, n = 35), first-episode psychosis (FEP, n = 39), and healthy controls (HC, n = 33)." (PMID 40637145, 2025). "Family history of psychotic disorders and certain inflammatory biomarkers, such as elevated C-reactive protein (CRP) and interleukin-6 (IL-6), have also been implicated in transition risk." (PMID 41254065, 2025). "Elevated IL-6 and TNF-α levels have also been consistently observed in individuals at clinical high risk for psychosis (CHR-P) and in first-episode psychosis (FEP) patients, suggesting their involvement in illness onset and progression." (PMID 40637145, 2025). "Regarding adjustment for BMI, tobacco smoking, and cannabis use, previous meta-analyses of individuals with recent and chronic psychotic disorders have shown elevated plasma IL-6 levels after adjusting for BMI and tobacco smoking." (PMID 39911538, 2025). "They found significantly elevated C-reactive protein (CRP) levels and interleukin 6 (IL-6) in the psychosis group compared to the controls unaffected by psychosis." (PMID 38911703, 2024). "A proof-of-concept study employing a randomised, parallel-group, double-blind, placebo-controlled design testing the effect of IL-6 inhibition on anhedonia in patients with psychosis." (PMID 36963796, 2023). "Functional assessment of IL-6/STAT3 signalling in immune cell subsets and their response to exogenous IL-6 stimulation will inform abnormal immune response in psychosis and allow measurement of response to tocilizumab at the cellular level." (PMID 36963796, 2023). "Recent meta-analysis shows elevated levels of IL-6 in the serum of patients with medication-naïve first episode psychosis." (PMID 35873262, 2022). "Interleukin (IL)-6 stands out for being increased both in the cerebrospinal fluid and blood of patients with psychosis, even before antipsychotic initiation." (PMID 36572669, 2022). "IL-6 had a significant but weak positive correlation with psychosis age of onset (r = 0.33, p = 0.003)." (PMID 36572669, 2022). "For example, elevated pro-inflammatory cytokines, including tumour necrosis factor-α and interleukin-6, were observed in patients with psychosis and CMD." (PMID 36008755, 2022).
psychosis (continued). "Contradictory data have been published concerning IL-6 increase in first-episode psychosis and acute relapse, and positive correlations between IL-6 level and illness duration, depressive symptoms and worse mental and physical wellbeing have been proposed." (PMID 35873262, 2022). "An increased concentration of IL-6 and decline of IL-17 in serum has been revealed in individuals at ultra-high risk (UHR) for psychosis, which explains the association that increased IL-17 levels can improve disease condition." (PMID 35493075, 2022). "A statistically significant positive correlation was observed between serum concentrations of UA and IL-6 in exacerbation, and with IL-17 after treatment and in the stabilization of psychosis." (PMID 35237183, 2021). "We found a statistically significant positive correlation between serum concentrations of UA and IL-6 in exacerbation and with IL-17 after treatment and in the stabilization of psychosis." (PMID 35237183, 2021). "For example, a previous study in this cohort reported higher levels of inflammatory cytokines Interleukin 6 and C Reactive Protein to be related to psychosis, and there are a number of other factors that influence these pathways." (PMID 33067055, 2020). "These beneficial effects can be explained by (i) the pathologic elevation of blood interleukin-6 and C-reactive protein levels in psychotic disorders, and (ii) IFX’s ability to reduce these elevated levels." (PMID 32390850, 2020). "We were also unable to test mediation reciprocally, ie, with IL-6 as a mediator between IR and PEs/psychotic disorder." (PMID 29635418, 2019). "We also found that, using both cut-offs for IR, there is a statistical interaction between IL-6 and IR for the outcome of both PEs and psychotic disorder at age 18 years." (PMID 29635418, 2019). "Antipsychotic-naïve patients with first-episode psychosis show elevated IL6, TNFα, IFNγ, IL17, and TGFβ levels compared with healthy controls." (PMID 30407606, 2019). "It was observed that the serum levels of IL-2 and IL-6 are increased in first episode drug-naïve patients with psychosis, and that IL-3 levels are significantly increased in patients with chronic schizophrenia." (PMID 26649857, 2017). "Our work suggests that increases in blood cytokines, especially in IL-6, IL-8 and TNFα, persist beyond early psychosis and can be found in chronic patients even when stabilised on antipsychotic medications." (PMID 28923068, 2017). "Epidemiological studies have shown that elevations in maternal C-reactive protein (CRP) and pro-inflammatory markers, such as cytokines IL-8 and TNFα, in addition to elevations in IL6 in childhood, predict psychotic disorder." (PMID 27650124, 2016). "Increased levels of IL-6 appears in medication-naïve patients with first episode of psychosis and acutely relapsed inpatients, whereas elevated levels of IL-6 at the age of 9 doubles the risk of developing psychosis later in life." (PMID 25886254, 2015). "To date, only few studies have investigated cytokine levels in subjects with first-episode psychosis, reporting higher serum or plasma levels of IL-1β, IL-6, IL-12, INF-γ, TNF- α, TGF- β and soluble IL-2 receptor." (PMID 22749891, 2013). "For example, studies of participants with 22q11.2 deletion syndrome (22q11.2DS) (a neurogenetic disorder whose phenotype includes both immunodeficiency and ID/psychotic disorder) found higher levels of inflammatory markers (C-reactive protein, IL-6, IL-10, TNFα) compared with healthy individuals." (PMID 40869088, 2025). "Specifically, the largest subthreshold psychosis study to investigate IL-6 is part of the Avon Longitudinal Study of Parents and Children (ALSPAC), which found serum IL-6 at age 9 was associated with PLEs at age 18 but not age 13 after adjusting for many sociodemographic factors." (PMID 38141839, 2024).
psychosis (continued). "Nevertheless, IL-6 especially should be considered as a valid candidate state marker, while it should be highlighted that it is also the most widely accepted blood-based trait marker for psychotic disorders." (PMID 39691789, 2024). "However, no interventional studies in patients with psychosis, stratified using inflammatory markers, have been conducted to assess the therapeutic potential of targeting IL-6 in psychosis and to elucidate potential mechanism of effect." (PMID 36963796, 2023). "The primary objective of this study is to test whether IL-6 contributes to the pathogenesis of first episode psychosis and to examine potential mechanisms by which IL-6 affects psychotic symptoms." (PMID 36963796, 2023). "In addition, we found a statistically significant, but weak positive correlation between serum concentrations of UA and IL-6 in exacerbation (p = 0.01, r = 0.220) and with IL-17 after treatment and in the stabilization of psychosis (p = 0.01, r = 0.34)." (PMID 35237183, 2021). "IL-1, IL-6, IL-12) were elevated in a subset of psychosis spectrum patients." (PMID 34363013, 2021). "Our mediation analysis suggests that IR does not mediate the association between IL-6 and PEs/psychotic disorder." (PMID 29635418, 2019). "Indeed, a molecular association between IL-6, NOX2 and PV has been previously reported in the ketamine model of psychosis." (PMID 31694174, 2019). "Model 2, where non-CNS dysfunction emerges as a consequence of psychosis, is supported by meta-analytic evidence that resolution of acute psychosis is associated with normalization of previously elevated cytokines (IL-1β, IL-6, and TGF-β)." (PMID 29743584, 2019). "The authors suggested that IL-1β, IL-2, and IL-6 could serve as markers for psychosis, while TNF-α, IL-17, and IFN-γ were still elevated after antipsychotic treatment." (PMID 30766494, 2018). "Similarly, IL-1β, IL-6 and TNFα levels in serum of drug-naïve patients with first-episode psychosis were reduced after risperidone treatment." (PMID 28358316, 2017). "Furthermore, it has been found that IL-6 level positively correlates with duration of untreated psychosis." (PMID 25214388, 2015). "Existing meta-analyses have suggested that patients with psychosis may exhibit an imbalance between pro-inflammatory cytokines (e.g., IL-1β, IL-6) and anti-inflammatory cytokines (e.g., IL-10), which could underlie immune dysregulation in the early stages of the illness." (PMID 41008291, 2025). "Meta-analytic evidence also indicates that treatment with antipsychotic medication is associated with a reduction in with IL-6, whereas IL-12 and TNF-α remain raised despite treatment, suggesting that cytokines may function as both state and trait markers of psychosis." (PMID 36946486, 2024). "Our primary hypothesis is that inhibition of IL-6 signalling with a single intravenous infusion of anti-IL6R mAb, tocilizumab, in individuals with psychosis and elevated IL-6 at baseline, will attenuate symptoms of anhedonia and amotivation in patients with psychosis, relative to placebo." (PMID 36963796, 2023). "Lower variability of IL6 in patients, coupled with a robust difference in mean concentration, could instead be interpreted as this parameter representing a core (or at least more uniformly present) component in the immunobiology of psychosis." (PMID 30407606, 2019). "This study aims to investigate the relationship among IL-6, TNF-α, and neurocognitive performance in early psychosis." (PMID 40637145, 2025). "Risperidone treatment significantly lowered levels of IL-6 and TNF-α in patients with chronic disease, while this effect was not evident in individuals experiencing their first episode of psychosis." (PMID 40153412, 2025). "A psychosis signature (ρ = 0.27; P = .002) differentiated ROP from CHR-P with elevated IL-6, TNF-α, and reduced CRP, alongside GMV shifts in corticothalamic circuits." (PMID 41405910, 2025).
psychosis (continued). "The found that serum IL-6 and CSF IL-6 levels were significantly elevated in acute confusional state compared to other NPSLE manifestations (cognitive dysfunction, psychosis)." (PMID 37841263, 2023). "In patients with psychotic disorders, the most frequent psychiatric manifestation in DGS, Th-17, Th-1 and Th-2 cells are increased with consequent elevation of proinflammatory cytokine IL-6 and IL1β." (PMID 36835652, 2023). "Our previous studies have also found associations between peripheral inflammatory markers, especially interleukin 6 (IL-6) and interferon gamma (IFN-γ), and psychotic disorders." (PMID 36675612, 2023). "Our previous research showed that higher serum levels of IL-6 and IFN-γ predicted a poor response to antipsychotic medication after 12 weeks of treatment in patients with first episode psychosis." (PMID 33667853, 2021). "In first-episode psychosis, interferon-γ (IFN-γ), IL-1RA, IL-1β, IL-6, IL-8, IL-10, IL-12, sIL-2R, TGF-β, and TNF were all significantly increased, and levels of IL-4 were significantly decreased." (PMID 32256401, 2020). "Age, sex, illness duration, smoking, and BMI were all unrelated to IL-6 and TNF-α increase in first-episode psychosis." (PMID 32256401, 2020). "The findings of elevated IL6, IL17, and IFNγ in psychosis appear robust, as elevations are also seen in sensitivity analyses, indicating they are unlikely due to confounding or other nonspecific factors." (PMID 30407606, 2019). "Some studies have shown a link between gestational levels of IL-6 and offspring ASD, psychosis, and developmental delays." (PMID 29531226, 2018). "Our finding aligns with the part of the literature that did not observe elevated IL-6 levels in FEDN psychosis patients." (PMID 41008291, 2025). "Our findings suggest that peripheral inflammation, particularly IL-6 and TNF-α, may selectively impact social cognitive functioning in early psychosis." (PMID 40637145, 2025). "In our study, IL-6 concentrations in the patients with FEDN psychosis were not significantly higher compared to the healthy control group." (PMID 41008291, 2025). "For example, a stress-induced inflammatory response was observed in psychosis patients (characterised by selective release of cytokines, including IL-6), which was not seen in unaffected siblings or healthy controls." (PMID 38710421, 2024). "Similarly, IL-6 and IL-4 are seen to be elevated in CHR-P compared to controls with baseline IL-10/IL-6 ratio and vascular endothelial growth factor (VEGF) also shown to be elevated in CHR-P individuals who transitioned to psychosis." (PMID 38710421, 2024). "However, several studies, including meta-analyses, found elevated levels of IL-6, IL-10, and TNF-α in first-episode drug-naïve (FEDN) psychosis patients and first-episode SCZ patients, the majority of whom were using antipsychotics." (PMID 37491201, 2023). "The FIRS, due to increased IL-6 levels following a maternal SARS-CoV-2 infection, may induce a wide range of adverse neurodevelopmental sequelae, such as autism, psychosis, and neurosensory deficits, later in life, similar to certain bacterial infections." (PMID 35637442, 2022). "In the whole blood of individuals with first episode psychosis (FEP), DICER1 overexpression may depend on the treatment status and IL-6 peripheral levels." (PMID 33149139, 2020). "Mean levels of IL6 (g = 0.62), TNFα (g = 0.56), interferon-γ (IFNγ) (g = 0.32), transforming growth factor-β (g = 0.53), and interleukin-17 (IL17) (g = 0.48) were elevated in psychosis." (PMID 30407606, 2019). "Stojanovic and colleagues (2014) studied IL6 and CRP levels in ARMS, psychotic disorder and normal controls and observed elevated IL6 in the combined ARMS and psychotic disorder groups compared to controls, and non significant elevations among ARMS who transitioned compared to those who did not." (PMID 27650124, 2016).